BRCA1 (BRCA1 DNA repair associated)
Diseases named in the same sentence as BRCA1 in open-access papers (continued):
Sharing a sentence is not in itself a finding about the gene and the disease.
breast cancer (continued). "High penetrance inherited breast cancer is mainly caused by pathogenic mutations in the BRCA1 and BRCA2 genes." (PMID 27087880, 2016). "Genetic testing for mutations in BRCA1 or BRCA2 identifies women at a high-risk of developing breast cancer; however, to date the only highly effective primary breast cancer prevention strategy is prophylactic bilateral mastectomy." (PMID 27893411, 2016). "In fact, the main objective of the present study was to investigate the contribution of BRCA1/2 mutation in early-onset breast cancer in Algerian women and to better understand the genetic risk factors associated with this disease." (PMID 26997744, 2016). "The breast cancer susceptibility gene BRCA1 is well known for its function in double-strand break (DSB) DNA repair." (PMID 26941120, 2016). "The risk of breast cancer by the age of 70 years has been reported as 57%-65% when there was BRCA1 mutation and 45%-49% when there was BRCA2 mutation." (PMID 27643881, 2016). "We showed that mammary tumors deficient for both p16 and Brca1 are highly aggressive, metastatic, and enriched for TICs." (PMID 27811360, 2016). "In breast cancer, forexample, BRCA1 and BRCA2 are susceptibility genes thataccount for around 25% of families with hereditary breast cancer." (PMID 27192130, 2016). "At the age of 70 years old, the mean cumulative breast cancer risks for BRCA mutation carriers are 47%-66% (BRCA1) and 40%-57% (BRCA2) in western countries." (PMID 27257965, 2016). "The expectation is that these tumors would react to therapy similarly to BRCA1-associated breast cancers including sensitivity to cisplatin or PARP inhibitors." (PMID 27626685, 2016). "Germline mutations in breast cancer susceptibility genes BRCA1 and BRCA2 confer a high risk of breast and ovarian cancer." (PMID 27257965, 2016). "Management of women who are considered high-risk for the development of breast cancer is controversial, especially in women who carry a BRCA1 or BRCA2 mutation as they can develop cancers at an earlier age." (PMID 28133583, 2016). "Specifically, parenchymal texture descriptors have demonstrated a strong cross-validated ability in predicting both risk for breast cancer (0.58 ≤ AUC ≤ 0.85) and BRCA1/2 mutation status (0.53 ≤ AUC ≤ 0.93)." (PMID 27645219, 2016). "This preliminary evidence suggests a potential contribution of BRCA1 5382insC mutation to breast cancer development in Uzbek population." (PMID 29138730, 2016). "We probed the nuclear material of breast cancer cells (HCC1937 line) that harbors a homozygous BRCA1 mutation (BRCA15382insC)." (PMID 27583302, 2016). "The same research group recently completed a study to further evaluate the use of platinum-based neoadjuvant chemotherapy for women with triple-negative, BRCA1 mutated breast cancer." (PMID 26873719, 2016). "On the other hand, the authors report that cumulative exposure to sex hormones, especially estrogen, is probably associated to breast cancer risk in BRCA1 mutation carriers." (PMID 27129401, 2016). "Recently, there has been a resurgence of interest in platinum-based chemotherapy including the use of platinum in patients with BRCA1-associated breast cancer which is known for its germline deficiency in DNA damage repair via homologous recombination (HR)." (PMID 27626685, 2016). "The common hereditary forms of breast cancer have been primarily attributed to the inheritance of mutations in the BRCA1 or BRCA2 genes." (PMID 26981296, 2016).
breast cancer (continued). "Less than 20 % of familial breast cancer patients who undergo genetic testing for BRCA1 and BRCA2 carry a pathogenic mutation in one of these two genes." (PMID 26758370, 2016). "In this study, we have conducted a genome-wide association study (GWAS) to identify genetic risk factors associated with mammary tumour predisposition in the ESS breed in addition to BRCA1/2 and ESR1." (PMID 27158822, 2016). "A total of 50 mRNA transcripts were also overexpressed in BRCA1/2-deficient breast cancer relative to sporadic breast cancer (p < 0.1)." (PMID 27566577, 2016). "In this regard, it was observed that females with increased BRCA1 blood methylation have a 3.5-fold increased risk for early-onset breast cancer with histological features commonly seen in tumors arising in women with germline BRCA1 mutations." (PMID 27999265, 2016). "BRCA1-associated breast cancer is often triple-negative or basal-like, which commonly confers poor prognosis." (PMID 27590516, 2016). "There is also expression of the Δ9/10 isoform that is similar to wildtype BRCA1 expression levels in the breast cancer patient control (heterozygous mutation carrier)." (PMID 26884819, 2016). "The increased risk for breast cancer is associated, among others, with a personal or family history of the disease and inherited gene mutations in BRCA1 and BRCA2 breast cancer susceptibility genes." (PMID 27974927, 2016). "Five BRCA mutation-positive patients had a second cancer: two previously had breast cancer (both BRCA1 mutation carriers), one previously had melanoma and two had synchronous endometrial cancer (all BRCA2 mutation-carriers)." (PMID 27406733, 2016). "A high percentage of BRCA1-associated hereditary and sporadic breast cancers are triple negative and are more likely to occur among pre-menopausal women of African American descent." (PMID 28164176, 2016). "About 15% of women with familial breast cancer are implicated to have mutation in BRCA1 and BRCA2 genes, also, all women with ovarian cancer are affected by some mutation in these genes." (PMID 27351029, 2016). "In this study, we tried to find a correlation between the clinicopathological characteristics of breast cancer and BRCA1/2 mutation status." (PMID 27129401, 2016). "Recently, we and others were able to show that RANK and RANKL are also critical regulators of BRCA1-mutation-driven breast cancer." (PMID 27881737, 2016). "Among the 94 known risk loci from white European and three from Asian populations, only 24 contained SNPs with some evidence of association (P<0.05) with breast cancer risk among BRCA1 mutation carriers alone." (PMID 27117709, 2016). "The present study was the first to investigate the PS and QOL of breast cancer patients who received BRCA1/2 genetic testing and to investigate the psychological experience of BRCA1/2 mutation carriers in mainland China." (PMID 27428375, 2016). "This dataset contains 359 patients with breast cancer, among which there were 22 BRCA1 mutation cases, 32 BRCA2 mutation cases and 305 sporadic cases." (PMID 27566577, 2016). "The determination of BRCA1/2 mutation status among women with a personal history of breast cancer and a strong family history of breast cancer has increased in importance." (PMID 27650678, 2016). "Cisplatin was recommended for this patient, as breast cancers harboring germline BRCA1 mutations are highly sensitive to cisplatin chemotherapy." (PMID 27245685, 2016). "In Part 2 BRCA1- or BRCA2-mutated HER2-negative breast cancer patients will be randomized between standard capecitabine 1250 mg/m2 BID day 1–14 q day 22, versus 2 cycles carboplatin-olaparib followed by olaparib monotherapy 300 mg BID." (PMID 27323902, 2016). "The results also suggest that genotype 1R/1R and 1R/0R can reduce the risk of breast cancer in BRCA1+ carriers." (PMID 27148484, 2016).
breast cancer (continued). "We aimed to investigate the distribution of both somatic and germline BRCA1/2 variants in unselected Chinese breast cancer patients, and explore their roles in tumor phenotype and disease prognosis." (PMID 27257965, 2016). "In our previous study, we reported that the most common recurrent mutations in Chinese women at high risk for breast cancer are c.5470_5477del8 in BRCA1 and c.3109C > T in BRCA2, which were reported to be the putative founder mutations." (PMID 26852015, 2016). "The estimated lifetime risk of breast cancer is 1–5 % in male BRCA1-mutation carriers and 5–10 % in male BRCA2-mutation carriers versus 0.1 % in the general population." (PMID 27377827, 2016). "Future work on with a higher n-number and in various ethnic groups is warranted in order to confirm that BRCA1 promoter methylation is an applicable and reliable predictive and diagnostic biomarker for breast cancer patients." (PMID 27027444, 2016). "Functional loss of BRCA1 by germline or somatic mutation or by promoter methylation is associated with more than one third of basal-like breast cancers and cell lines." (PMID 27811360, 2016). "Together, our data demonstrate the potential usefulness of breast tumor GEMM-derived secretome biomarkers for non-invasive diagnosis of human BRCA1-deficient breast cancer." (PMID 27566577, 2016). "According to literature, the average cumulative risks of developing breast cancer for BRCA1 and BRCA2 mutation carriers by the age of 70 years are 65% and 45%, respectively, and those of ovarian cancer are 39% and 11%, respectively." (PMID 26997744, 2016). "As a consequence, little is known about the psychological feelings and psychosocial conditions of Chinese breast cancer patients who have a BRCA1 or BRCA2 mutation, leading to a significant deficiency in nursing care and intervention." (PMID 27428375, 2016). "To test the effect of Neat1 knockdown on Brca1-deficient mammary tumor development, we perform in vivo tumorigenicity analysis on scramble (as a control) and Neat1 shRNA transfectants of primary tumor cell cultures." (PMID 27556296, 2016). "It has been reported that 5 μM ABT-888 leads to ~90% reduction in the clonogenic survival of MDA-MB-436 BRCA1 mutated breast cancer cell line." (PMID 27196668, 2016). "Hormonal exposure and the overall lifetime number of ovulatory cycles are modifiers of breast cancer risk among BRCA1 mutation carriers." (PMID 27246982, 2016). "Among the 507 unselected breast cancer patients, 40 (7.9%) had a germline BRCA1/2 P/LP variant, and 9 (1.8%) had a somatic BRCA1/2 pathogenic variant." (PMID 27257965, 2016). "We present the case of a 48-year-old Caucasian female with a BRCA1 gene mutation associated with bilateral breast cancer." (PMID 26868636, 2016). "In this study, we demonstrate a significant inverse relationship between plasma OPG levels and breast cancer risk among 206 women with an inherited BRCA1 or BRCA2 mutation." (PMID 27893411, 2016). "Phosphorylation of S6RP has been shown to confer resistance to PARP inhibitors in BRCA1-deficient breast cancers through regulation of DNA damage response and the HR repair process." (PMID 26909613, 2016). "Although only less than 10% of sporadic ovarian cancer and 5% of breast cancer harbored BRCA1 mutations, BRCA1 methylation is observed in approximately 11–14% of breast cancer and 5%–31% of ovarian cancer." (PMID 26967246, 2016). "The frequently observed VNTR association with in BRCA1+ and BRCA2+ breast cancer group indicates that VNTR polymorphism in the XRCC5 promoter is associated with altered risk of breast cancer in BRCA1+ and BRCA2+ carriers." (PMID 27148484, 2016).
breast cancer (continued). "Neoadjuvant chemotherapy with cisplatin has been applied in patients with BRCA1-associated breast cancer and TNBC; however, the outcomes of cisplatin-based neoadjuvant chemotherapy are heterogeneous." (PMID 27626685, 2016). "Starting at the age of 25, the risk of developing breast cancer rises continuously in BRCA1-mutation carriers." (PMID 27881737, 2016). "Multiple breast cancer susceptibility genes such as BRCA1 and BRCA2 with high penetrant disease-associated mutations have been shown to segregate in families with breast cancer by linkage studies." (PMID 27806084, 2016). "BRCA1 status was associated with aggressive tumor phenotype and worse disease progression in early stage breast cancer patients." (PMID 27257965, 2016). "This is presumed to be why many reports on the effects of early diagnosis on inherited breast cancer have combined BRCA1 and BRCA2 mutation carriers together to provide sufficient enough cases to arrive at a significant conclusion." (PMID 27087880, 2016). "Our study provides evidence showing that VNTR polymorphisms in the XRCC5 promoter is associated with risk of familial breast cancer with BRCA1+ and BRCA2+ predisposition." (PMID 27148484, 2016). "Even though they face high lifetime breast cancer risks (approximately 50%), young women with BRCA1/2 mutations face relatively low 10-year breast cancer risks (1%–2%)." (PMID 27417623, 2016). "Despite genetic heterogeneity, variations among different ethnicities and differences in penetrance, BRCA1 gene mutations have been proven related to an increased risk of hereditary breast cancer, accounting for as much as 81%." (PMID 27027444, 2016). "Currently no specific guidelines for systemic therapy in the metastatic setting are available for BRCA1- or BRCA2-mutated breast cancers." (PMID 27323902, 2016). "Preclinical studies in breast cancer models showed that BRCA1 or BRCA2 deficient cell lines, when compared to BRCA proficient cell lines, are extremely sensitive to PARP1 inhibition." (PMID 27323902, 2016). "RB is a major target for genomic disruption in BRCA1 mutant human breast cancers and loss of both RB and BRCA1 is a feature of basal-like breast cancers." (PMID 27811360, 2016). "Olaparib is an oral PARP inhibitor that was shown in a phase II trial to be useful against BRCA1/2-associated advanced breast cancers." (PMID 27977696, 2016). "For instance, in MCF7 human breast cancer cells, AhR activation was linked to silencing of BRCA1 by recruitment of DNA methyltransferases to its promoter region." (PMID 27243009, 2016). "Most information on EMT transcription in breast cancer refers to the triple-negative basal-like sub-type associated with BRCA1 mutations which increase Slug protein stability but data on ER-positive cancers are also available." (PMID 26797644, 2016). "Compared with sporadic tumors, BRCA1-deficient breast cancers are also five to ten times more likely to express cytokeratins 5/6 (CK5/6) associated with the mammary basal (myoepithelial) cells." (PMID 27313062, 2016). "BRCA1 is required for the execution of taxane-induced apoptosis, and at least some data indicate that taxane-containing regimens show limited efficacy towards BRCA1-associated breast cancers." (PMID 27555886, 2016). "This mutation in the BRCA1 gene is associated with deficiencies in transcription-coupled repair events and high incidences of breast cancer." (PMID 27583302, 2016). "Hereditary breast cancer arising in the setting of germline mutations in BRCA1 and BRCA2 is recognized to generally sort with the BLBC and luminal subtypes of breast cancer, respectively." (PMID 27708239, 2016).
breast cancer (continued). "Previously, we had identified 11 BRCA carriers in a series of 40 selected breast cancer patients at increased risk for carrying a mutation in the BRCA1 and BRCA2 genes." (PMID 27129401, 2016). "In this regard, it should be noted a significant increase in the risk of developing diabetes after a breast cancer diagnosis appears to occur in women with BRCA1/2 mutation." (PMID 26943589, 2016). "Our top SNP within this gene, rs611646 has been associated with breast cancer in interaction with BRCA1 in a study of Chinese Han subjects indicating its possible functionality." (PMID 26248682, 2016). "One SNP (rs11891642) in the intron region of BRE was reported associated with an increased risk of breast cancer in a BRCA1 mutation carrier cohort." (PMID 26848770, 2016). "The discovery of BRCA1 and 2 genes predisposing to breast cancer has improved identification of cases linked to genetic susceptibility." (PMID 27129401, 2016). "CPM is performed most frequently among women with a family history of breast cancer, BRCA1/2 mutation status, and younger age at diagnosis." (PMID 27650678, 2016). "The LCR for breast cancer in women harboring germline mutations in this gene is similar to the risk of carriers of germline mutations in BRCA1 (44 to 68 % until 70 years of age), whereas the risk of ovarian cancer ranges from 11 to 40 %." (PMID 26770289, 2016). "For instance, germline mutations in breast cancer susceptibility gene 1/2 (BRCA1/2) and the Fanconi anemia (FA) genes are associated with increased susceptibility of breast cancer." (PMID 27705915, 2016). "We report that TOP1 and CDH3 were expressed to a higher extent in BRCA1-related breast carcinomas relative to sporadic breast carcinomas, highlighting their potential clinical usefulness for breast cancer detection in women with a BRCA1 mutation." (PMID 27566577, 2016). "ACACA is a target gene of BRCA1, preventing its dephosphorylation through BRCA1 protein banding to it, while BRCA1 is widely known as a breast cancer susceptibility gene." (PMID 27506935, 2016). "It correlates with breast cancer incidence, causing BRCA1 loss of function due to a modified expression profile of the gene." (PMID 27027444, 2016). "Our data suggest that BRCA1/2 mutations are responsible for a significant proportion of breast cancer in Algerian young women." (PMID 26997744, 2016). "A previous study has demonstrated that loss of BRCA1 results in increased ROS accumulation and sensitivity to oxidative stress in breast cancer cells." (PMID 27486766, 2016). "Linkage analysis and fine-mapping led to the discovery of BRCA1/2 and other high-penetrance and medium-penetrance genes, which are mutated in about a quarter of all familial breast cancer cases." (PMID 27716388, 2016). "We demonstrated that loss of both p16 and Brca1 led to metastatic, basal-like, mammary tumors with the induction of EMT and an enrichment of tumor initiating cells." (PMID 27811360, 2016). "When combining the PARP1 inhibitor olaparib with cisplatin in a BRCA1-mutated breast cancer mouse model, the combination induced a larger response than either of the two compounds alone." (PMID 27323902, 2016). "Although hereditary breast cancers account for 5–10 % of incident breast cancers, women who inherit a mutated form of the BRCA1/2 gene have up to 87 % risk of developing breast cancer by the age of 70 years." (PMID 27645219, 2016). "For example, we searched for cancer drug trials that were recruiting breast cancer patients with BRCA1 mutation in the United States." (PMID 27801815, 2016).